TLR9 (toll like receptor 9)
Diseases named in the same sentence as TLR9 in open-access papers (continued):
Sharing a sentence is not in itself a finding about the gene and the disease.
pulmonary arterial hypertension (1 paper, 2025). Pulmonary arterial hypertension (PAH) is a group of diseases characterized by mean pulmonary artery pressure >20 mmHg and elevated pulmonary arterial resistance leading to right heart failure. "Firstly, activation of TLR9 participates in the pathogenesis of monocrotaline-induced pulmonary arterial hypertension in rats via activation of the NF-κB-IL-6 pathway." (PMID 41303627, 2025). "Summarizing, Hb stimulates lipid peroxidation of cell membranes, which may be the initial step in a locally limited inflammatory response mediated by TLR9, resulting in the presentation of an activated PASMC phenotype and ultimately leading to the development of pulmonary arterial hypertension." (PMID 41303627, 2025).
pustular psoriasis (1 paper, 2024). "AP1S3 mutations in pustular psoriasis reduce degradation activity in lysosomes and may favor intracellular accumulation of bacterial DNA complexes in neutrophils, leading to sustained TLR9 activation." (PMID 38448036, 2024).
renal dysfunction (1 paper, 2015). "Moderate renal ischemia induced renal dysfunction but did not decrease animal well-being and was not regulated by TLR9." (PMID 26361210, 2015).
rheumatic diseases (1 paper, 2019). "The polymorphisms rs5743708 for the TLR2 and the rs187084_rs5743836 TLR9 haplotypes appear to be involved in the development of clinical forms of PsA and can be a possible therapeutic target for the rheumatic diseases." (PMID 31781672, 2019).
rhinosinusitis (1 paper, 2012). "In rhinosinusitis specimens, confocal analysis showed a clear TLR4/TLR9 co-localization in the cellular infiltrate of the sub-mucosa associated with marked damage of the epithelium." (PMID 22577387, 2012).
Schistosoma haematobium infection (1 paper, 2013). "We set out to characterize B cell subsets and B cell responses to B cell receptor and Toll-like receptor 9 stimulation in Gabonese schoolchildren with Schistosoma haematobium infection." (PMID 23505586, 2013).
schwannoma (1 paper, 2020). A benign, usually encapsulated slow growing tumor composed of Schwann cells. "RT4 schwannoma cells were used as an experimental in vitro model for Schwann cells to study the effect of fMLF on the regulation of Fpr2 and TLR9—receptors for mitochondrial peptides and DNA, respectively." (PMID 33322305, 2020). "We studied RT4 schwannoma cells to investigate the regulation of Fpr2 and TLR9 after stimulation with fMLF as a prototypical formylated peptide." (PMID 33322305, 2020). "RT4 schwannoma cells were used as an in vitro model of Schwann cells to investigate the course of cytoplasmic events following stimulation of fMLF and CpG —ligands for Fpr2 and TLR9, respectively." (PMID 33322305, 2020).
secondary progressive multiple sclerosis (1 paper, 2014). A multiple sclerosis with a clinical course characterized by a progressive accumulation of neurological disability, independent of relapses, following an initial relapsing-remitting (RR) phase. "MIS416 is a microparticulate immune response modifier that targets myeloid cells, activating cytosolic receptors NOD2 and TLR9, and has completed a phase 1b/2a trial for the treatment of secondary progressive multiple sclerosis." (PMID 24498172, 2014).
Senile plaques (1 paper, 2024). Senile plaques are extracellular deposits of amyloid in the gray matter of the brain. "Additionally, other studies have demonstrated the increased expression of TLR2, TLR4, TLR5, TLR7, TLR9, and the co-receptor CD14 in microglial cells surrounding senile plaques in the brain tissues of patients with AD and AD mouse models." (PMID 38360834, 2024).
septic peritonitis (1 paper, 2016). Septic peritonitis is an inflammatory condition of the peritoneum that occurs secondary to microbial contamination. "In this study, we tried to investigate the correlation of TLR9 expression with IL-17 production in PMNs during septic peritonitis and found that both sTLR9 and IL-7 could be expressed in the PMNs infiltrated into the peritoneal cavity of the mice infected with E. coli." (PMID 27057095, 2016).
sleep disorder (1 paper, 2025). A change from the patient's baseline sleeping pattern, in the hours slept and/or an alteration/dysfunction in the stages of sleep. "Future studies should focus on the role of BANK1 in mood and sleep disorders, aiming to identify other than TLR7 and TLR9 upstream regulators involved in this pathway." (PMID 41516251, 2025).
soft tissue sarcoma (1 paper, 2024). A malignant neoplasm arising from muscle tissue, adipose tissue, blood vessels, fibrous tissue, or other supportive tissues excluding the bones. "Combining radiation therapy with TLR9 agonist CpG delays tumor growth in soft tissue sarcomas through a CD8+ T cell–dependent mechanism." (PMID 39133651, 2024).
spondyloarthritis (1 paper, 2019). "The polymorphism rs5743708 for the TLR2 and the rs187084_rs5743836 TLR9 haplotypes appear to be involved in the development of clinical forms of SpA and can be a possible therapeutic target for the spondyloarthritis." (PMID 31781672, 2019).
Streptococcus pneumonia (1 paper, 2014). "On the same line, it was demonstrated that TLR9 played a protective role in airway infection with Streptococcus pneumonia." (PMID 24595157, 2014).
subarachnoid hemorrhage (1 paper, 2024). A serious neurological disorder characterized by intracranial hemorrhage into the subarachnoid space. "Immunohistochemical methods and Western blot showed increased levels of TLR9 and a slight increase in TLR4 and FRP2 following both subarachnoid hemorrhage as well as the application of artificial cerebrospinal fluid over time, although the individual periods were different." (PMID 39839349, 2024).
T cell lymphoma (1 paper, 2022). "The expression levels of TLR1, TLR4, TLR7, and TLR9 were higher in LNs of patients with AOSD than in LNs of those with T cell lymphoma and reactive lymphadenopathy." (PMID 35715478, 2022). "The expression levels of TLR1, TLR4, TLR7, and TLR9 were higher in LNs of patients with AOSD than in those with T cell lymphoma and reactive lymphadenopathy." (PMID 35715478, 2022). "The expression levels of TLR1, TLR4, TLR7, and TLR9 increased in the LNs of patients with AOSD compared to that in reactive LN or T cell lymphoma." (PMID 35715478, 2022). "Furthermore, the percentage of inflammatory cells expressing TLR4, TLR7, and TLR9 in LNs from patients with AOSD was significantly greater than that in patients with T cell lymphoma (p = 0.001) and reactive LNs (p = 0.012)." (PMID 35715478, 2022). "The expression level of TLR2 was similar in LNs from patients with T cell lymphoma and AOSD; however, TLR1, TLR4, TLR7, and TLR9 expression levels were higher in the LNs of patients with AOSD than in T cell lymphoma." (PMID 35715478, 2022).
tetanus (1 paper, 2021). A serious infectious disorder that follows wound contamination by the Gram-positive bacterium Clostridium tetani. "Thus, this CTL epitope was fused to a universal T-helper epitope, either a synthetic pan HLA-DR epitope (PADRE) or a natural tetanus (Tet) sequence, with or without CpG 7909, a toll-like receptor 9 (TLR9) synthetic oligonucleotide antagonist, and the fusion showed positive immunogenicity profiles." (PMID 34070277, 2021).
thrombophilia (1 paper, 2017). A condition characterized by an abnormally high level of thrombi. "We analyzed TLR9 rs5743836 polymorphism in Malmö thrombophilia study patients; a prospective follow-up study of 1465 VTE patients by Taqman PCR." (PMID 28321710, 2017). "However, on multivariate Cox regression analysis, after adjusting with location of DVT, family history of VTE, mild and severe thrombophilia, TLR9 polymorphism was significantly associated with the risk of VTE recurrence (HR 5.94, CI 1.25–28.13, P = 0.025)." (PMID 28321710, 2017). "We found a significant association between TLR9 rs5743836 polymorphism and VTE recurrence in female patients, independent of location of DVT, family history of VTE & mild and severe thrombophilia." (PMID 28321710, 2017). "Similarly, in unprovoked VTE patients, TLR9 polymorphism was significantly associated with higher risk of VTE recurrence in female patients (HR 5.94, 95% CI 1.25–28.13) after adjusting for family history, risk of thrombophilia and DVT location." (PMID 28321710, 2017).
tonsillitis (1 paper, 2017). Inflammation of the tonsillar tissue. "Furthermore, we examined the expression of IFN-α and TLR9 in tonsil samples of IgAN patients who suffered from tonsillitis." (PMID 29403161, 2017).
transient cerebral ischemia (1 paper, 2012). "Among diverse TLRs, it has been reported that, after transient cerebral ischemia, induction of TLR2 predominates among TLRs, followed by TLR4 and TLR9." (PMID 22873409, 2012).
Ureaplasma infection (1 paper, 2013). "Furthermore, when we investigated whether TLR9 was triggering signalling from the endosomes in response to Ureaplasma infection, it was shown that following Ureaplasma infection, TLR9 co-localised in the endosomes with the signalling adaptor molecule MyD88." (PMID 23593431, 2013).
uremia (1 paper, 2023). A clinical syndrome associated with the retention of renal waste products or uremic toxins in the blood. "Exogenous MtDNA also resulted in a further increase in cytosolic MtDNA and TLR9 levels in uremia-conditioned HCMECs." (PMID 36755219, 2023).
visceral leishmaniasis (1 paper, 2017). A severe form of leishmaniasis characterized by irregular bouts of fever, substantial weight loss, swelling of the spleen and liver, and anemia (which may be serious). "Studies in human disease have shown that patients with visceral leishmaniasis present an increase in TLR4 and TLR9 expression after treatment with miltefosine, generating a strong proinflammatory response which is important in disease resolution." (PMID 29358935, 2017).
zoster (1 paper, 2021). "In recent years, the U.S. FDA has approved several TLR adjuvanted vaccines, including TLR4 based HPV vaccine (Cerarix) and zoster vaccine (Shingrix), and TLR9 based HBV vaccine (Heplisav)." (PMID 34766005, 2021).
tumor (568 papers, 2005 to 2026). "Most strikingly, TLR9 agonists like cytosine-phosphate-guanine (CpG) oligonucleotides that showed promising anti-tumor immunity in mice caused severe adverse events in human trials due to the broader TLR9 expression on human immune cells." (PMID 40806379, 2025). "In this study, we found the TLR9 pathway in tumor microenvironment was also implicated in tumor progression." (PMID 40038250, 2025). "The activation of TLR9 not only induces the expansion of tumor-associated DCs, but elicit the antitumor immune response by synergizing with PD-L1 inhibitors." (PMID 41293166, 2025). "For example, high TLR9 expression is associated with the activation of dendritic cells, which in turn can stimulate an effective anti-tumor response." (PMID 39451226, 2024). "Literature data indicate that increased expression of TLRs, particularly TLR2, TLR4, and TLR9, in tumor cells and the tumor microenvironment is associated with GC progression." (PMID 39451226, 2024). "Some studies have indicated that TLR-9 is associated with increased tumour malignancy, whereas others have suggested that it contributes to the immune response against the tumour." (PMID 39201739, 2024). "In our HPV-negative OSCC cohort, smoking, alcohol use, stage, nodal status, tumor size, recurrence, and TLR9 rs187084 polymorphism were significant prognostic factors for OS, according to univariate Cox regression analysis." (PMID 38850110, 2024). "The upregulation of TLR9 in breast cancer has been associated with various clinicopathological characteristics, including more aggressive tumor features, such as higher grade, larger size, and increased lymph node involvement." (PMID 39123407, 2024). "Top 25% patients with high TLR9 expression exhibited significantly higher tumor mutational burden than that of low TLR9 expression group (bottom 25% patients) (5.81 mutations/Mb vs 4.36 mutations/Mb; P = 0.0059, Welch’s two-sample t-test)." (PMID 37435086, 2023). "The same molecules significantly decreased after treatment with DNase I and were reduced in TLR-9 deficient cells, with a concomitant decrease in tumor cells migration and invasion, suggesting TLR-9 as a possible therapeutic target in preventing recurrences." (PMID 36838231, 2023). "Combining pembrolizumab treatment with toll-like receptor 9 agonists is associated with an elevation in tumor-infiltrating DCs as well as clinical benefits in preliminary studies." (PMID 35794399, 2023). "Conjugation of STAT3ASO to CpG oligonucleotide, a TLR9 agonist, facilitates targeting of TLR9-expressing immune cells, such as human and mouse tumor-associated MDSCs and macrophages, plasmacytoid DCs, and B cells but not T cells." (PMID 38259453, 2023). "TLR7 and TLR9 agonists have been used to activate tumor-associated pDCs and showed some clinical benefit." (PMID 35311157, 2022). "The association between TLR3, TLR4, and TLR9 expressions and tumor aggressiveness and poor prognosis in HCC was obtained from 30 patients with HCC." (PMID 35434373, 2022). "In conclusion, these findings indicate that there is an uneven distribution of TLR9high tumor samples, with a significant association between heavy alcohol consumption and tumors with higher expression levels of TLR9." (PMID 35990685, 2022). "A virus-like particle encapsulating a CpG-A TLR9 agonist (CMP-001) has recently been reported to cause tumor regression in syngeneic hepa mouse models of HCC, with a greater antitumor activity of CMP-001 monotherapy than that of sorafenib or PD-L1 blockade." (PMID 34025657, 2021). "With regard to the fourth TLR sensing intracellular viral antigens, TLR9 has 4 SNPs which were found to be associated with several infectious, autoimmune, and neoplastic diseases." (PMID 33763088, 2021). "Studies utilizing TLR9 agonists as immune adjuvants in cancer vaccines comprising of tumor-associated antigens showed strong clinical induction of antitumor CD4+ and CD8+ T cells." (PMID 35008305, 2021).
tumor (continued). "Transient DC TLR9 activation has been associated with positive outcome; however, TLR9 signaling in, e.g., T cell or cancer cells can lead to tumor growth enhancement." (PMID 32225009, 2020). "Some researchers suggested that high expression of TLR9 is associated with tumor growth and migration, and it has been recognized as a new prognostic biomarker in cancer 11,12." (PMID 31892973, 2020). "It has been reported that stimulating tumor cells with a TLR9 agonist can lead to tumor cell death by inducing antitumor immunity associated with immunogenic or immunostimulatory cell death." (PMID 32483468, 2020). "Delivery of CpG-ODN directly into the tumour has been shown to reduce the immunosuppressive activity of monocytic MDSC (which express TLR9) and cause their differentiation into macrophages with direct tumouricidal capability." (PMID 33352882, 2020). "Several studies reported that the high expression of TLR9 is associated with tumor growth and migration, and it has been recognized as a new prognostic biomarker in cancer." (PMID 31892973, 2020). "A TLR9/IL-6/JAK/STAT3 pathway in tumor-associated myeloid cells plays an essential role in initiating the cancer recurrence after radiotherapy." (PMID 32788720, 2020). "In ESCC, TLR-3 overexpression was significantly correlated with worse clinical parameters, while higher levels of TLR-9 were positively associated with advanced tumour grade, lymph node and distant metastases." (PMID 33008143, 2020). "We found that tumor-released DNA causes accumulation, antigen uptake, and maturation of dendritic cells (DCs) in the tumor in a TLR9-dependent manner." (PMID 31619293, 2019). "The genotyping analysis showed that the presence of mutated allele -1237C (TLR9-1237 TC+CC) was associated with large tumor size (p = 0.017; OR (CI 95%) = 1.888 (1.11-3.19)) at diagnosis." (PMID 31886298, 2019). "Immunosuppression by the TLR2 and TLR9 combination regimen on host immune and tumor cells for controlling metastatic behavior was associated with a nominal effect on initial subcutaneously embedded tumor growth." (PMID 31508424, 2019). "Because TC-1 cells carry the wildtype TLR9 allele, loss of tumor control in TLR9−/− mice must be due to a host-intrinsic requirement for TLR9." (PMID 31619293, 2019). "Loss of HMGB1 leads to a defect in TLR9 signaling pathway and decreases tumor cell proliferation, whereas addition of HMGB1 leads to the activation of TLR9 signaling pathway and promotes tumor cell proliferation." (PMID 28969092, 2017). "We also showed that tumor TLR9 expression is associated with prognosis, but only among patients that have triple-negative tumors for which there are no targeted therapies." (PMID 27888633, 2016). "TLR9 overexpression has also been associated with an increased tumor grade in breast and ovarian cancers." (PMID 28116318, 2016). "It has been demonstrated that there is a strong association between TLR3, TLR4 and TLR9 expression and tumor aggressiveness and poor prognosis in HCC." (PMID 24932259, 2014). "More specifically, low tumor TLR9 expression upon diagnosis was associated with a significantly shortened disease-free-specific survival." (PMID 25101078, 2014). "Clinically, increased expression of TLR9 has been associated with higher tumor grade and worse prognosis." (PMID 25411122, 2014). "TLR9 expressed on tumor cells has been associated with increased cell proliferation and increased invasion potential." (PMID 25309546, 2014). "Surprisingly, the tumoricidal effects of RT+TLR9 agonist combination therapy were maintained in B cell-deficient mice, suggesting that immune cells, other than B cells, contribute to the control of tumor progression." (PMID 22666458, 2012). "To characterize the mechanism underlies the pivotal role of miR-574-5p in enhanced tumor progression induced by TLR9 signaling, we further evaluated the direct effect of miR-574-5p on the growth of 95D cells in vitro and in vivo." (PMID 23133627, 2012).